TM6SF2 (transmembrane 6 superfamily member 2)
Diseases named in the same sentence as TM6SF2 in open-access papers (continued):
Sharing a sentence is not in itself a finding about the gene and the disease.
steatosis (continued). "Previous experimental studies demonstrated that TM6SF2 siRNA inhibition was associated with a reduced secretion of triglyceride‐rich lipoproteins and an increased triglyceride aggregation in hepatocytes, whereas TM6SF2 overexpression was associated with reduced liver cell steatosis." (PMID 31309745, 2019). "Therefore, this study investigated the association of the TM6SF2 E167K variant with histological liver damage (i.e., steatosis, hepatic inflammation, and fibrosis) in patients with CHC by performing a systematic review and meta-analysis of the available literature." (PMID 28839198, 2017). "Notable single nucleotide polymorphisms (SNPs), including PNPLA3 rs738409, TM6SF2 rs58542926, MBOAT7 rs641738, and GCKR rs1260326, are consistently linked to steatosis, inflammation, and fibrosis in MASLD." (PMID 40943344, 2025). "Hispanic ethnicity and genetic polymorphisms in PNPLA3, TM6SF2, GCKR, MBOAT7, and HSD17B13 are associated with steatosis-related lipotoxicity and oxidative DNA damage, which can contribute to hepatocarcinogenesis." (PMID 40995256, 2025). "Background/Objectives: This study evaluated the association between polymorphisms in the PNPLA3, TM6SF2, HSD17B13, and SIRT5 genes and the severity of fibrosis and steatosis in metabolic dysfunction-associated steatotic liver disease (MASLD)." (PMID 39596570, 2024). "Two other studies showed that TM6SF2 rs58542926 E167K increased the risk of liver steatosis in patients with non-genotype 3 HCV infections and was also associated with the severity of steatosis." (PMID 37400794, 2023). "Transmembrane 6 superfamily member 2 (TM6SF2) activity is required for normal VLDL secretion, and impaired TM6SF2 activity causally contributes to NAFLD and is associated with steatosis, inflammation and fibrosis." (PMID 35453652, 2022). "The objective of this study was to determine the association between variants of PNPLA3, TM6SF2, and MBOAT7-TMC4 and the three histologic stages of NAFLD (steatosis, NASH, and fibrosis) in PLWHIV." (PMID 36110512, 2022). "The TM6SF2 p.E167K (c.499G>A) variant is important in patients with NAFLD, being associated with more severe steatosis, necroinflammation and advanced fibrosis/cirrhosis." (PMID 35096933, 2021). "Transmembrane 6 superfamily member 2 (TM6SF2) variants are also strongly associated with the presence of NAFLD and have been correlated with the severity of steatosis, NASH, and cirrhosis." (PMID 34073538, 2021). "In mice, the knockdown of TM6SF2 by adeno-associated virus (AAV)-delivered shRNA increased hepatic TG levels and, upon feeding high sucrose diet, led to the development of steatosis." (PMID 32443737, 2020). "The protective role of steatosis emerged from the evaluation of some genetic polymorphisms that are related to steatosis, such as single nucleotide polymorphisms (SNPs) in the PNPLA3 and TM6SF2 genes." (PMID 37632072, 2023). "For instance, several single nucleotide polymorphisms (SNPs) such as patatin-like phospholipase domain-containing protein 3 (PNPLA3), transmembrane six superfamily member 2 (TM6SF2) and membrane bound O-acyltransferase domain-containing 7 (MBOAT7) appear to be associated with steatosis progression." (PMID 35696400, 2022). "Further than the PNPLA3 and the TM6SF2 SNPs, we therefore tested the rs3750861 KLF6, the rs13412852 LPIN1, and the rs4880 SOD2 SNPs, which have demonstrated associations with fibrosis, steatosis and fibrosis, and again fibrosis, respectively, in previous studies on NAFLD patients." (PMID 29732362, 2018). "In contrast to what was observed for steatosis, a subgroup analysis did not demonstrate any confounds with obvious interference on the TM6SF2-fibrosis association (all P > 0.05)." (PMID 28839198, 2017). "The steatosis and transaminitis in Tm6sf2−/− mice were observed on a standard chow diet." (PMID 27013658, 2016).
steatosis (continued). "The presence of a non-synonymous variant of TM6SF2 (rs58542926) results in a misfolded protein, with accelerated degradation and reduced function, leading to retention of low-density lipoproteins (VLDL), promoting hepatic steatosis, inflammation, and fibrosis, accelerating the development of HCC." (PMID 40806538, 2025). "Our objective was to analyze the relationship between PNPLA3, TM6SF2, and MBOAT7-TMC4 and steatosis, steatohepatitis, and liver fibrosis in PLWHIV with NAFLD." (PMID 36110512, 2022). "As previously discussed, TM6SF2 gene knockout, inhibition of MDM2–ApoB interaction, HNF4α, GLS1 inhibition, and mTORC1 activation on VLDL lipidization have shown great potential for reducing steatosis by regulating VLDL to affect MASLD." (PMID 40723862, 2025). "The PNPLA3 mutation and initial steatosis grade were key predictors of MASLD improvement, while TM6SF2 (rs58542926) and MBOAT7 (rs641738) variants were not significant." (PMID 39125390, 2024). "Findings about the associations between transmembrane 6 superfamily member 2 (TM6SF2) rs58542926 and nonalcoholic fatty liver disease have not been consistently replicated, particularly in steatosis and fibrosis." (PMID 36353245, 2022). "As yet, the function of TM6SF2 is not known, and the molecular mechanism by which it regulates steatosis and HCC remains to be determined." (PMID 32443737, 2020). "In contrast, TM6SF2 rs58542926 and MBOAT7 rs641738 were not related to steatosis in our cohort." (PMID 35696400, 2022).
Cirrhosis (46 papers, 2015 to 2026). A chronic disorder of the liver in which liver tissue becomes scarred and is partially replaced by regenerative nodules and fibrotic tissue resulting in loss of liver function. "Genetic markers, such as single nucleotide polymorphisms (SNPs) in genes like PNPLA3 and TM6SF2, have been linked to an increased risk of liver fibrosis and cirrhosis." (PMID 40430206, 2025). "Genomic profiling: Advances in genome sequencing have enabled the discovery of genetic variants (e.g., PNPLA3, TM6SF2) linked to cirrhosis risk and progression." (PMID 40430206, 2025). "For that reason, TM6SF2 rs58542926 variant has been suggested as a potential risk factor for development of liver fibrosis and cirrhosis and linked to lipid abnormalities in chronic HCV patients." (PMID 36028802, 2022). "The analyses to detect TM6SF2 genetic association with advanced hepatic fibrosis were powered at > 88%, however, the same for determining predisposition to hepatic cirrhosis were underpowered (< 42%)." (PMID 36028802, 2022). "Conversely, carriage of rs187429064:G in TM6SF2 is associated with an increased risk of HCC in patients with cirrhosis." (PMID 34958182, 2022). "TM6SF2 variant rs58542926 has also been associated with an increased risk of developing advanced hepatic fibrosis and cirrhosis in patients with non-alcoholic fatty liver disease (NAFLD)." (PMID 30875804, 2019). "The rs58542926 polymorphic variant of the TM6SF2 gene is used to identify individuals with a higher susceptibility to chronic liver diseases, especially hepatocellular carcinoma, cirrhosis, alcoholic liver disease, and nonalcoholic fatty liver disease." (PMID 31795497, 2019). "The present study investigates if common missense functional variants p.I148M and p.E167K in PNPLA3 and TM6SF2 genes, respectively, associate with development of hepatic fibrosis and cirrhosis in a geographically novel cohort of Pakistani chronic hepatitis C (CHC) patients." (PMID 36028802, 2022). "In particular, our pooled results found that the TM6SF2 variant predicted the risk of cirrhosis." (PMID 28839198, 2017). "Metabolic factors, such as diabetes, obesity, and hypertension, as well as common genetic polymorphisms in the PNPLA3 and TM6SF2 genes, influence the severity of underlying liver histology and, thus, are likely to impact on risk of developing cirrhosis and HCC." (PMID 27213358, 2016). "No statistical significance was observed for the OR of SNPs in MBOAT7, HSD17B13, and TM6SF2 in MASLD-related cirrhotic HCC compared with cirrhosis." (PMID 40995436, 2025). "The lead variants at PNPLA3, TM6SF2, and APOE were either coding or in high LD with a coding variant and have all been previously implicated in the full spectrum of MASLD, including cirrhosis and HCC." (PMID 40823170, 2025). "Like the PNPLA3 variant, TM6SF2 rs58542926 contributes to the progressive liver disease in patients with MASLD, initiating from simple steatosis to progressive fibrosis and cirrhosis." (PMID 40725464, 2025). "In particular, phospholipase domain-containing 3 (PNPLA3) and transmembrane 6 superfamily member 2 (TM6SF2) are well known and replicated genetic markers that associated with hepatic fibrosis/cirrhosis, hepatitis, and hepatocellular carcinoma." (PMID 37403158, 2023). "Over 50% of cirrhosis patients had at least one risk variant in PNPLA3, MBOAT7 and GCKR, while 13.0% had at least one risk variant in TM6SF2." (PMID 36854015, 2023). "In total, 502 Pakistani CHC patients [242 males, median age 40 years, 220 with significant hepatic fibrosis, including 114 with cirrhosis] were genotyped for PNPLA3 and TM6SF2 variants using TaqMan genotyping assays." (PMID 36028802, 2022). "The TM6SF2 E167K variant is associated with NAFLD, fibrosis, and cirrhosis, as well as NAFLD-associated cancer." (PMID 34503201, 2021).
Cirrhosis (continued). "In this study, we aimed to investigate the contribution of previously implicated genetic risk factors (PNPLA3, TM6SF2, EGF, MTHFR) for the development of cirrhosis and HCC in the Croatian population." (PMID 34640639, 2021). "We examined the association of all-cause cirrhosis with six genetic variants previously reported to be associated with alcoholic or non-alcoholic cirrhosis: PNPLA3 I48M, TM6SF2 E167K, MBOAT7 rs641738, HSD17B13 rs72613567, HFE C282Y and SERPINA1 E366K." (PMID 32282858, 2020). "We replicated known associations of PNPLA3, TM6SF2, HFE and HDS17B13 variants with cirrhosis at genome-wide significance." (PMID 32282858, 2020). "Known NAFLD and cirrhosis risk alleles in PNPLA3 and TM6SF2 were also associated with both elevated cT1 and MRI-derived PDFF in our cohort." (PMID 32247823, 2020). "TM6SF2 is involved in very low-density lipoprotein (VLDL) secretion, and the rs58542926 variant has been associated with ALD cirrhosis, HCC, and NAFLD." (PMID 31340446, 2019). "In one prospective study of diabetic individuals, a PRS including PNPLA3, transmembrane 6 superfamily member 2 (TM6SF2) and SERPINA1 was associated with an increased risk of cirrhosis (p = 0.03) and, more interestingly, was associated with advanced fibrosis among those with FIB‐4 < 1.3 (p = 0.03)." (PMID 39412170, 2025). "Interestingly, the majority of SNPs identified as risk factors for alcohol-associated cirrhosis in recent GWAS reside in/around the genes related to lipid metabolism and lipid droplet biology (PNPLA3, HSD17B13, FAF2 and TM6SF2)." (PMID 37887024, 2023). "In addition, studies have pointed out that genetically-driven NAFLD-related genes such as PNPLA3 and TM6SF2 genes are associated with increased liver fat content and progression to NASH and cirrhosis." (PMID 35310993, 2022). "Nevertheless, in the present CHC patients of Pakistani origin we did not detect any significant effect of PNPLA3 and TM6SF2 variants in modulating serum markers of hepatic injury nor hepatic fibrosis and cirrhosis." (PMID 36028802, 2022). "The TM6SF2 rs58542926 E167K variant is also associated with hepatic fibrosis and cirrhosis, independent of potential cofounding factors such as body mass index (BMI), type 2 diabetes mellitus, and the PNPLA3 rs738409 genotype." (PMID 34503201, 2021). "SNP rs10401969 of the TM6SF2 gene also correlates with ALD cirrhosis." (PMID 31340446, 2019). "None of the TM6SF2 rs58542926 alleles or genotypes were linked with the risk of developing liver fibrosis or cirrhosis." (PMID 30875804, 2019). "In detail, variants rs738409 in PNPLA3, rs641738 in MBOAT7, and rs58542926 in TM6SF2 are associated with increased triglyceride production, accumulation of very low-density lipoprotein (VLDL) and triglycerides and increased risk of developing cirrhosis, respectively." (PMID 36835291, 2023). "Also, no significant impact of PNPLA3 and TM6SF2 variants on hepatic fibrosis and cirrhosis of CHC background was highlighted in some of such studies from other populations." (PMID 36028802, 2022). "Since BMI was independently associated with hepatic fibrosis and cirrhosis in these analyses, we therefore also stratified CHC patients according to BMI status into obese (BMI ≥ 25) and non-obese (BMI < 25) sub-groups and analyzed for any potential genetic associations of PNPLA3 and TM6SF2 variants." (PMID 36028802, 2022). "PNPLA3 and TM6SF2 variants do not appear to modulate development of hepatic fibrosis or cirrhosis in present CHC patients of Pakistani origin, and may be of more relevance in liver pathology involving abnormalities in hepatic fat accumulation." (PMID 36028802, 2022). "However, such evidence is relatively limited for TM6SF2 where only a couple of studies reported overrepresentation of TM6SF2 rs58542926 risk allele in CHC patients displaying hepatic scarring (fibrosis and cirrhosis)." (PMID 36028802, 2022).
Cirrhosis (continued). "Notably, TM6SF2 rs58542926 combined with PNPLA3 rs738409 may have additive value in predicting ALD cirrhosis progression; additionally, both of them had a potential risk for HCC development in ALD patients." (PMID 34068269, 2021). "Another study reported that the combination of PNPLA3, TM6SF2 and HSD17B13 predicted NASH-cirrhosis and HCC in general population settings." (PMID 36266438, 2022). "Scientists have reported that TM6SF2 rs58542926 mutation is one of the important genetic factors leading to NAFLD, and it is also associated with advanced hepatic fibrosis/cirrhosis independent of potential confounding factors such as age, BMI, T2D." (PMID 38149094, 2023). "By univariate analysis, the SNPs in PNPLA3, TM6SF2 and PDCD1 rs7421861 were significantly different in NAFLD-HCC versus controls, but none retained significance after regression analysis including age, sex and cirrhosis." (PMID 33808740, 2021). "The results of our study showed that direction for TM6SF2 rs58542926 between fibrosis and cirrhosis groups was different, but the significance level was not reached and this genetic variant alone or combined with PNPLA3 risk genotype was not linked with liver fibrosis or cirrhosis." (PMID 30875804, 2019).
liver disease (40 papers, 2016 to 2026). "This phenomenon is known to involve both PNPLA3 and TM6SF2 and explains the discordant effects of some genetic variants on liver disease versus coronary artery disease." (PMID 40297446, 2025). "Other variants, such as TM6SF2 E167K and MBOAT7, are linked to MASLD progression, with TM6SF2 showing a paradoxical protective effect against cardiovascular events despite worsening liver disease." (PMID 40869400, 2025). "We replicated previous GWAS results, reporting a significant association of TSLP and RORA gene variants with asthma and GCKR, PNPLA3, TRIB1 and TM6SF2 gene variants with the risk of developing liver diseases, notably NAFLD/NASH." (PMID 30978214, 2019). "To elucidate the biologic function of TM6SF2 and the pathogenic mechanisms of TM6SF2-associated liver disease, we generated mice in which expression of the gene was ablated by insertional mutagenesis using a gene trap vector." (PMID 27013658, 2016). "Their frequency was less common in the Mexican population, which might hide their influence on liver disease, given the well-established role of TM6SF2 and NCAN variants in liver disease." (PMID 40806538, 2025). "Genetic mutation of transmembrane 6 superfamily member 2 (TM6SF2) plays a role in liver diseases." (PMID 36263163, 2022). "Similarly, genetic studies have demonstrated that a variant in the transmembrane 6 superfamily member 2 ((TM6SF2) gene is not only associated with an increased risk of liver disease in ALD." (PMID 35160340, 2022). "This review will explore the bidirectional relationship between metabolic syndrome and NAFLD, and will also discuss recent insights from studies of PNPLA3 and TM6SF2 genotypes that may give insight into how and why metabolic syndrome features and liver disease are linked in NAFLD." (PMID 26978356, 2016). "Polymorphisms in liver disease–risk genes such as PNPLA3 and TM6SF2 have been linked directly to liver metabolism." (PMID 40371650, 2025). "This study evaluated the distribution of PNPLA3 rs738409, TM6SF2 rs58542926, and HSD17B13 rs6834314 and overall survival of HCC patients with metabolic dysfunction-associated steatotic liver disease (MASLD-HCC) and viral-related HCC (VIRAL-HCC)." (PMID 40725464, 2025). "Conversely, our previous study did not identify acquired somatic mutations in genes with strong germline associations with liver disease (e.g. PNPLA3, TM6SF2)." (PMID 35474605, 2022). "So far, multiple genes have been shown to be associated with increased liver disease risk, such as CTLA-4, IL-18, transmembrane 6 superfamily member 2 and GSTM1." (PMID 34886817, 2021). "The steatogenic alleles in PNPLA3, TM6SF2, GCKR and MBOAT7 all associated with increased risk of ICD‐defined ‘other diseases of liver’ (K76), which includes NAFLD (n = 408 455, P = 0.0075–2 × 10−12)." (PMID 29280273, 2018). "Variants in genes, such as Patatin‐like phospholipase domain‐containing protein 3 (PNPLA3) and Transmembrane 6 superfamily member 2 (TM6SF2), not only increase susceptibility to liver diseases but are also influenced by the rapid changes in the sociodemographic profile of countries worldwide." (PMID 40833357, 2026). "Better understanding of the biological functions of TM6SF2 in cells affected by atherosclerosis will elucidate the effects of TM6SF2 in atherosclerosis and liver diseases, which may aid in developing new approaches for treating cardiovascular diseases." (PMID 36139452, 2022). "Similarly, the variant rs58542926 E167K in transmembrane 6 superfamily member 2 (TM6SF2) gene which is involved in VLDL secretion, has been associated with the pathogenesis of NAFLD and with liver disease severity." (PMID 30642126, 2019). "Such potential examples of genotypes that are associated with a dissociation between liver disease and metabolic syndrome are patatin-like phospholipase domain-containing protein-3 (PNPLA3) (I148M) and transmembrane 6 superfamily member 2 protein (TM6SF2) (E167K) genotypes." (PMID 26978356, 2016).
liver disease (continued). "None of the polymorphisms of TM6SF2, MBOAT7, GCKR, nor the PRS, were associated with increased risk of development of severe liver disease in the full cohort." (PMID 36166317, 2022). "In conclusion, genetic variants in PNPLA3, TM6SF2, MBOAT7, and HSD17B13 do not seem to impact the short-term regression of portal hypertension." (PMID 33917196, 2021). "Host genetic factors that increase the prevalence of NAFLD in the general population, such as polymorphisms in the genes encoding patatin-like-phospholipase domain-containing 3 (PNPLA3) and transmembrane 6 superfamily member 2 (TM6SF2), may also impact liver disease in PLWH." (PMID 35746590, 2022). "Our findings indicate that fibrosis progression in steatotic liver disease is mediated by an interaction of environmental risk factors (obesity, insulin resistance, alcohol consumption) and genetic risk variants, such as PNPLA3 and TM6SF2, but not by genetic variants alone." (PMID 41492318, 2026).